ABCB1 (ATP binding cassette subfamily B member 1)
Diseases named in the same sentence as ABCB1 in open-access papers (continued):
Sharing a sentence is not in itself a finding about the gene and the disease.
cancer (continued). "In contrast, in resistant cancer cells with ABCB1/ABCC1 overexpression, afatinib can not enhance the cytotoxicity of doxorubicin, a substrate drug for both ABCB1 and ABCC1, suggesting that afatinib probably did not interact with ABCB1 or ABCC1." (PMID 25436978, 2014). "Further studies demonstrated MK-571’s ability to increase the intracellular accumulation of MRP1 substrates, which may be a way to overcome the chemoresistance of cancer cells overexpressing ABCC1, but not ABCB1." (PMID 41154409, 2025). "Furthermore, RuZ had a low affinity for ABCG2 and ABCB1, thus, indicating that RuZ is not extruded from MDA-MB-231 cancer cells." (PMID 37408573, 2023). "Our findings indicate that treatment with furmonertinib at concentrations ranging from 50 nM to 500 nM did not produce a significant impact on the protein expression of ABCB1 in NCI-ADR-RES and KB-V1 cells, nor on ABCG2 in S1-MI-80 and H460-MX20 cancer cells over a period of 72 h." (PMID 37762275, 2023). "Through CRISPR/Cas9 gene editing, we recently reported that 110α and 110β subunits of the phosphoinositide 3-kinase (PI3K) signaling pathway are potential targets for reversal of ABCB1/P-gp- and ABCG2/BCRP-mediated cancer MDR in a manner independent of AKT expression." (PMID 35459184, 2022). "However, the efficacy of MCA was not significantly different between KB-3-1 and KB-C2 cancer cells, indicating that MCA was efficacious in the ABCB1-overexpressing cell line, i.e., there was no resistance to MCA." (PMID 32676451, 2020). "Besides, acerinol also demonstrated no impact on the ABCB1 mRNA level in both HepG2/ADM and MCF-7/ADR multi-drug resistant cancer cells." (PMID 31766413, 2019). "Together these results suggest that inhibitors of drug transport, not just limited to ABCB1/MDR, and inhibitors of peroxisomes and fatty acid metabolism may be effective in blocking cancer cells’ response to chemotherapy." (PMID 31052165, 2019). "ABCA1, an ABC transporter, but not ABCB1, ABCC1 or ABCC2, might be involved in the anti-cancer drug resistance observed in DU145 cells stably overexpressing embigin." (PMID 30041429, 2018). "In addition, there was no significant alteration insensitivity of cancer cells to compounds that were not ABCB1 or ABCG2 substrates, which suggests that the efficacy of osimertinib to reverse MDR is specific to ABCB1 and ABCG2." (PMID 27649127, 2016). "However, cellular ABCB1 and SLC35F2 levels did not indicate YM155 sensitivity in YM155-naïve cells, as indicated by drug response data derived from the Cancer Therapeutics Response Portal (CTRP) and the Genomics of Drug Sensitivity in Cancer (GDSC) databases." (PMID 32357518, 2020). "Moreover, in the event that there are tumors harboring FGFR alterations and ABCB1 overexpression, erdafitinib would remain effective against FGFR, as we have shown that ABCB1 does not confer significant resistance to erdafitinib in cancer cells." (PMID 32466597, 2020). "We discovered that unlike other ABCB1- and ABCG2-interacting tyrosine kinase inhibitors such as dasatinib and imatinib, erdafitinib was equally cytotoxic in multidrug-resistant cancer cells overexpressing either ABCB1 or ABCG2 as in the corresponding drug-sensitive parental cancer cells." (PMID 32466597, 2020). "Furthermore, clinical trials using ABCB1 inhibitors to increase tumor uptake of chemotherapeutics had little success, partly because patients were not always screened for MDR status and partly because ABCB1 is not known to mediate MDR in some of the tested cancers." (PMID 31729540, 2020).
tumor (829 papers, 1989 to 2026). "P-glycoprotein (P-gp), the most studied protein of the ABC transporter family, is encoded by the ABCB1 gene encodes and affects the uptake of chemotherapy drugs by pumping them out of tumor cells." (PMID 40352594, 2025). "Gene rearrangement and tumor mutation are important mechanisms for controlling and regulating the ABCB1 gene promoter, which will lead to overexpression of the ABCB1 gene and induce drug resistance in tumors." (PMID 39337463, 2024). "The mutation at position 2677 reduces the transport capacity of ABCB1, allowing the drug to accumulate in tumor cells and achieve a good therapeutic effect." (PMID 38674402, 2024). "Among this group of exporters, the most studied ABC transporter is the P-glycoprotein (multidrug resistance 1 (MDR1)/ATP-binding cassette sub-family B member 1 (ABCB1)), as its functional activity in tumor cells underlies resistance to multiple drugs." (PMID 39857239, 2024). "Namely,performance in a doxorubicin-resistant tumor setting caused by theoverexpression of drug exporter ABCB1." (PMID 39088428, 2024). "The overexpression of ABCB1 (P-gp, also known as P-glycoprotein) by tumor cells is a definitive cause of MDR." (PMID 37299013, 2023). "We recently reported a series of point mutations in the ABCB1/MDR1 gene encoding P-gp of clinical tumor biopsies." (PMID 37373385, 2023). "One of the underlying mechanisms in tumor resistance is the aberrant activation of PI3K/AKT pathways that upregulates the expression of ABC transporters (P-gp/ABCB1, MRP1/ABCC1, and BRCP/ABCG2), and pro-survival molecules such as Bcl-2 and IAPs." (PMID 37627134, 2023). "Second, we investigated single-cell expression levels of the common drug-efflux pump ABCB1, which has been implicated in multidrug resistance across a number of tumor types." (PMID 36867694, 2023). "The MDR is mainly related to the over-expression of P-glycoprotein (P-gp) in tumor cells, which is a drug transporter encoded by MDR1 (ABCB1) gene and can expel DOX from cells, resulting in reduced anti-tumor effect of DOX." (PMID 36919676, 2023). "The observed synergy involves the proapoptotic protein PUMA and the modulation of drug transporters such as ABCB1, affecting the concentration of cytotoxic drugs in the tumor-associated microenvironment." (PMID 36603521, 2023). "MRNAs encoding ABCG2 and ABCB1 were more abundant in CD44+CD133+ tumor-initiating Caco-2 cells than in ΔCD44+CD133+ non-tumor-initiating Caco-2 cells (i.e., the CD44−CD133- and CD44−CD133+ fractions)." (PMID 35433695, 2022). "NVP-CGM097 can also reverse the multidrug resistance of tumor caused by ABCB1 (ATP binding cassette subfamily B member 1) by blocking the drug efflux mediated by ABCB1 and improving the therapeutic effect of chemotherapy." (PMID 35831864, 2022). "Previous studies have shown that the overexpression of ABCB1 confers chemoresistance and is directly associated with a higher tumor stage and grade in PCa." (PMID 36135731, 2022). "The ABCB1 negativity was also associated with hypertensive status, large tumour size and low lymph node status." (PMID 33801148, 2021). "In a 3D multicellular tumor spheroid model, deficiency in ABCB1 restrained tumor spheroid growth and restore sensitivity to paclitaxel in MDR tumor spheroids." (PMID 34977876, 2021). "For example, it has been suggested that ABCB1 expression is the highest in tumour-associated macrophages in breast stromal compartments, rather than the tumour samples themselves." (PMID 33801148, 2021). "In contrast, significant downregulation of the LXR and ABCB1 in the early stage of CRCs is associated with the accumulation of CHOL within tumor cells, and subsequently promotes the initial phase of CRCs development." (PMID 33568147, 2021). "P-gp (MDR1/ABCB1) relies on ATP energy to pump hydrophobic drugs from cells, which reduces intracellular drug concentration and causes resistance in tumor cells." (PMID 34306145, 2021).
tumor (continued). "Further tests using the 3D multicellular tumor spheroid model suggested that deficiency in ABCB1 restrained tumor spheroid growth and restore sensitivity to paclitaxel in MDR tumor spheroids." (PMID 34977876, 2021). "Disruption of the ABCB1 gene can cause a decrease in intestinal polyps and tumour incidence, while the disruption of the ABCC1 gene has been linked to reduced tumour incidence and increased tumour latency in mouse models." (PMID 33801148, 2021). "ATP binding cassette subfamily B member 1 (ABCB1) is one of the genes involved in MDR that by encoding P-glycoprotein (P-gp) inhibits the entering of anti-tumor drugs into cells." (PMID 33478512, 2021). "ABCB1 and ABCG2 are the most basic multidrug resistance protein in different tumor tissues, ABCB1 encodes p-gp, and ABCG2 encodes BCRP." (PMID 32258043, 2020). "Hypomethylation of the ABCB1 promoter in tumor and serum samples was associated with a shorter median overall survival of the patients." (PMID 33066132, 2020). "The ABCB1 gene, one of the ABC superfamily, encodes for a transmembrane glycoprotein (P-glycoprotein) capable of pumping IM out of the tumor cell." (PMID 32974132, 2020). "In contrast, rs2032582 was the only ABCB1 SNP to show significant association with a pathological characteristic of BC, namely, tumor size (p value = 0.03)." (PMID 31391850, 2019). "Overexpression of certain ABC transporters such as ABCG2/BCRP and ABCB1/Pgp in tumor cells is linked with resistance to chemotherapy." (PMID 29713280, 2018). "After adjustment for age, clinical stage, residual disease, histological type and tumor grade, high ABCB1 status remained to be a significant risk factor for adverse OS and PFS." (PMID 27812204, 2016). "The methylation status of CpG3-CpG7 of the ABCB1 promoter in tumor tissues was associated with the menopause status of the patients (p = 0.008, p = 0.008, p = 0.002, p = 0.008 and p = 0.017, respectively)." (PMID 27689338, 2016). "In human and Chinese hamster tumor cell lines, some mutations of the ABCB1 gene have been reported to be associated with drug resistance." (PMID 29061940, 2015). "We showed that ABCB1 polymorphisms were able to influence CRC susceptibility related to tumor localization and patient gender." (PMID 25355168, 2014). "Because of its poor tumor specificity, inhibition of ABCB1 efflux transporter in humans has caused strong side effects, preventing this to be a viable treatment option." (PMID 24819355, 2014). "Stratification for tumor stages confirmed this trend and again showed that in advanced tumors (stage IVa), poor survival in association with low ABCB1 expression." (PMID 25275603, 2014). "We demonstrate, by immunohistochemistry in patient tissue microarrays, that ABCB1 is expressed in 43% of tumours and is significantly associated with high-risk." (PMID 24887326, 2014). "High ABCB1 mRNA tumor expression was associated with both favorable progression-free survival (PFS, p = 0.0357) and overall survival (OS, p = 0.0535)." (PMID 25275603, 2014). "Consistent with the presence of this mutation, we observed nuclear localisation of β-catenin together with high ABCB1 levels in all three tumours that are heterozygous for mut β-catenin mutation." (PMID 22460269, 2012). "Underlying this study is the objective of maintaining ABCB1 expression at the blood brain barrier, while modulating expression on tumours or other epithelial barriers." (PMID 23133566, 2012). "Tumours unmethylated for the middle region of the ABCB1 CpG island were associated with mutations in the loop domains L2/L3 (p = 0.022), a region that has previously been shown to be associated with lack of response to doxorubicin based treatment." (PMID 20338046, 2010). "The 3435CC genotype has usually been associated with higher levels of ABCB1 mRNA and protein and increased drug efflux in normal tissues and tumours, although some discrepancies have been reported, especially in Japanese populations." (PMID 20628376, 2010).
tumor (continued). "We also analyzed whether there was a correlation between germline variants in the ABCB1 gene and P-glycoprotein expression in the tumor, with marginal results." (PMID 39771563, 2024). "Furthermore, the expression of ABCB1 genes, which have been associated with tumor multidrug resistance, was increased in the 3D culture systems compared to that of the 2D culture system." (PMID 38256154, 2024). "The opposite result might relate to the association of ABCB1 with molecular status, tumor characteristics, demographics, and genetic variants, which still needs more laboratory and clinical data to be explored and validated." (PMID 37857015, 2023). "ABCB1 mRNA (encoding MDR-1) was above 3 FC in only one tumor sample (Canine 4), suggesting that increased MDR-1 protein levels may occur post-translationally." (PMID 36077749, 2022). "ABCB1 is one of the MDR-associated genes involved in drug efflux from tumor cells." (PMID 34425750, 2021). "Nonetheless, the efficacy of these newer generation of MDRT inhibitors remained also limited which might be caused by heterogeneity of the tumor cells regarding ABCB1 expression, drug penetration, and other simultaneous existing resistance mechanisms." (PMID 34858183, 2021). "This leads to the potential that some of the mutations in MFD-1 may be chemotherapy induced, however the frequency of mutations observed in SEMA5A and ABCB1 in previous studies of chemotherapy naïve OAC point to these mutations being tumour specific." (PMID 27600491, 2016). "Similarly, when adjusted for residual disease (N = 6), age (N = 4), FIGO stage (N = 4), histological type (N = 2) and tumor grade (N = 1), high ABCB1 expression remained significantly associated with OS (HR, 1.94; 95% CI: 1.52–2.46)." (PMID 27812204, 2016). "Similarly, when adjusted for residual disease (N = 4), age (N = 3), FIGO stage (N = 2), histological type (N = 1) and tumor grade (N = 1), high ABCB1 expression remained significantly associated with PFS (HR, 2.13; 95% CI: 1.60–2.83)." (PMID 27812204, 2016). "The activation of the MAPK/ERK pathway was associated with the upregulation of P-gp and the ABCB1 gene in several human tumor cells, which indicated that the MAPK/ERK pathway regulates ABCB1/P-gp expression at both the transcriptional and posttranscriptional levels." (PMID 29061940, 2015). "This reduced aggressiveness could be attributed to additional mutational burden however, transfection of ABCB1 in the U2OS cell line eliminated tumour formation and lung metastases in a subcutaneous xenograft model and was causally linked to reduced aggressiveness." (PMID 36434179, 2023). "We considered whether tumours with a propensity to undergo structural rearrangement may be more likely to have fusion events, but we found no indication of an association between the frequency of SV in a sample and ABCB1 fusion positivity." (PMID 30894541, 2019). "In addition, the ABCB1 mutations may indicate a potential mechanism for chemotherapy resistance that was observed in the primary tumour." (PMID 27600491, 2016). "In contrast to this, some tumour cell types predominantly express ABCB1 on the cell surface, which leads to resistance to xenobiotics." (PMID 41111259, 2026). "Inhibition of ABCB1 is a promising therapeutic strategy to resensitize resistant tumor cells to paclitaxel." (PMID 41613813, 2026). "One possibility is that while ABCB1 upregulation is an important mediator of taxol resistance in this tumor, in the subclone represented by this particular OCM, this mechanism has been subverted by another adaptation that offers a proliferative advantage." (PMID 40466638, 2025). "Notable associations include survival related to ABCB1 and ABCC2 variants, tumor occurrence linked to CYP2B6 rs3745274, and renal function affected by multiple pharmacogenes." (PMID 40761554, 2025).
tumor (continued). "Intratumoral administration of melatonin effectively overcame CDDP resistance in CAL 27/ABCB1 xenografts, significantly reducing tumor volume and promoting apoptosis." (PMID 41189280, 2025). "Upon exposure to chemotherapeutics, drug-resistant cells increase release of ABCB1-carrying EVs, mediated by Rab8B.Furthermore, in drug-sensitive tumor cells, Rab5 downregulation accelerated the recycling of these exosomes to the plasma membrane." (PMID 40881702, 2025). "The results indicated that compound punigratine, as a substrate of the ABCB1 protein, can compete with anti-tumor drugs by inhibiting the efflux function of ABCB1 protein." (PMID 39796265, 2025). "Ciprofloxacin reverses multidrug resistance and enhances tumor cell-sensitized ABCB1 substrates to maintain chemo-drug concentration in cells." (PMID 40643531, 2025). "In CAL 27/ABCB1 xenografts treated with melatonin, tumor cells exhibited a morphology completely different from those treated with CDDP." (PMID 41189280, 2025). "It has been shown that the expression of ABC transporter proteins, particularly multidrug resistance protein 1 (MDR1), is closely associated with tumor development, and that many chemotherapeutic drugs, such as uptake and distribution, are affected by ABCB1." (PMID 41306963, 2025). "There were numerous reports from the 1980s and 1990s investigating the prognostic value of P-glycoprotein/ABCB1 in many tumor types." (PMID 40723843, 2025). "The drug efflux pump ABCB1 plays a key role in promoting chemoresistance by actively effluxing a wide range of chemotherapeutic agents from tumor cells." (PMID 41189280, 2025). "Concurrently, high tsMHC-II-expressing tumor cells exhibited a closed chromatin state at the ABCB1 promoter and an open state at TOP2A." (PMID 40495188, 2025). "The potency of carmustine (~2-fold increase in median survival) and irinotecan (79% decrease in tumor volume) also increased in vivo when ABCB1 expressions or activities dwindled." (PMID 39861164, 2025). "This process is mediated by the downregulation of ATP-binding cassette subfamily B member 1 (ABCB1) to regulate tumor resistance." (PMID 39931083, 2025). "ABCB1 was a key downstream target of CYLD for regulating tumor growth and therapeutic resistance both in vitro and in vivo, CYLD knockdown promoted the translocation of p65 to nucleus which increased ABCB1 expression through transcriptional activation." (PMID 40012003, 2025). "The FPD modification significantly enhanced tumor targeting and amplified the Su sensitivity by reducing ABCB1/P-gp expression induced by GELNs." (PMID 41243691, 2025). "The findings reveal new molecular mechanisms of melatonin in reversing chemoresistance and highlight a potentially effective treatment for tumor cells overexpressing ABCB1." (PMID 41189280, 2025). "Molecularly targeted therapies against drug transporter proteins like ABCB1 are increasingly effective in clinical tumor treatment." (PMID 40265153, 2025). "Bufalin, a bioactive compound used in traditional Chinese medicine, downregulates ABCB1 protein levels and ATPase activity, enhancing docetaxel retention and apoptosis in vitro and reducing tumour growth in xenograft models." (PMID 40806254, 2025). "The results showed that tumor specimens with higher ABCB1 expression (cases 3 and 4) displayed higher resistance to doxorubicin than that with lower ABCB1 expression (cases 1 and 2), which affirmed a clinical significance of ABCB1 in mediating MDR." (PMID 41328326, 2025). "Several studies have indicated that overexpression of ABCB1 in tumor cells is correlated with increased levels of H3ac, H3K4me2, H3K4me3, H3K9ac, and H4ac in the promoter region of the gene." (PMID 40265153, 2025). "Clinically, elevated ABCB1 levels in tumour specimens correlate with a reduced taxane response and earlier relapse." (PMID 40806254, 2025). "Most of its tumor efficacy is influenced by efflux transporters; specifically, ABCB1, ABCG2, ABCC4 (MDR4), and ABCC6." (PMID 38646295, 2024).